OAT (ornithine aminotransferase)
Description:
Catalyzes the reversible interconversion of L-ornithine and 2-oxoglutarate to L-glutamate semialdehyde and L-glutamate.
Synonyms: HOGA; GACR; OATASE; OKT
Tractability: Small molecule: a structure with a bound ligand is known; a high-quality ligand is known; it has a high-quality binding pocket. PROTAC: ubiquitination databases record sites on it; its protein half-life has been measured; a small molecule that binds it is known.
Target class: Enzyme; Transferase
Gene: Protein-coding gene on chromosome 10 (124,397,298 to 124,419,760, reverse strand). Ensembl gene ENSG00000065154.
Subcellular location: Mitochondrion matrix
Subcellular location (Human Protein Atlas): Mitochondria; Nucleoplasm
Pathways (Reactome):
Metabolism: Glutamate and glutamine metabolism
Gene Ontology:
Molecular function: identical protein binding; ornithine aminotransferase activity; protein binding; pyridoxal phosphate binding; transaminase activity
Biological process: visual perception; L-glutamate catabolic process; L-glutamine catabolic process; L-proline biosynthetic process
Cellular component: mitochondrial matrix; mitochondrion
Genetic constraint (gnomAD): Loss-of-function variants: 28 observed, 39.65 expected, observed/expected ratio (o/e) 0.71, 90% interval 0.52 to 0.97. The upper end of that interval is the gene's LOEUF score, 0.97, which puts it in group 4 of 6, group 1 being the genes least tolerant of losing a copy. Missense variants: 405 observed, 507.61 expected, observed/expected ratio (o/e) 0.8, 90% interval 0.74 to 0.87. Synonymous variants: 165 observed, 191.5 expected, observed/expected ratio (o/e) 0.86, 90% interval 0.76 to 0.98.
Gene-disease validity (ClinGen):
ClinGen rates the evidence that OAT causes each of these diseases.
ornithine aminotransferase deficiency (autosomal recessive): Definitive.
Homologues: Orthologues: chimpanzee OAT (100% identical), macaque OAT (97% identical), dog OAT (92% identical), guinea pig OAT (92% identical), pig OAT (91% identical), mouse Oat (91% identical), rat Oat (91% identical), rabbit OAT (89% identical), tropical clawed frog oat.2 (80% identical), zebrafish oat (75% identical), Drosophila melanogaster Oat (69% identical), Caenorhabditis elegans oatr-1 (62% identical). Paralogues in human: AGXT2 (29% identical), PHYKPL (25% identical), ETNPPL (24% identical), ABAT (22% identical).
Diseases named in the same sentence as OAT in open-access papers:
OAT is named in the same sentence as 61 diseases in open-access papers, as found by Europe PMC text mining. Sharing a sentence is not in itself a finding about the gene and the disease. The quoted sentences say what the papers report.
Gyrate atrophy (17 papers, 2007 to 2025). "Gyrate atrophy is an autosomal recessive retinal degeneration caused by pathogenic variants in the gene encoding ornithine aminotransferase (OAT), a mitochondrial enzyme required for ornithine degradation." (PMID 40210192, 2025). "Gyrate atrophy is another rare autosomal recessive inherited chorioretinal dystrophy, and is due to mutations in the ornithine aminotransferase (OAT) gene." (PMID 39011458, 2024). "Gyrate atrophy of the choroid and retina is a rare autosomal recessive metabolic disorder caused by biallelic variants in the OAT gene, encoding the enzyme ornithine δ-aminotransferase." (PMID 37667371, 2023). "Gyrate atrophy of choroid and retina (GACR) is a chorioretinal degeneration caused by pathogenic variants in the gene encoding ornithine aminotransferase (OAT), an enzyme mainly expressed in liver." (PMID 36647689, 2023). "Ornithine‐δ‐aminotransferase (OAT) deficiency results in gyrate atrophy of the choroid and retina (GACR), a rare autosomal recessive inborn error of metabolism with progressive retinal degeneration." (PMID 36647689, 2023). "These include the novel association of 3-amino-2-piperidone with the rare OAT missense variant p.Leu402Pro; mutations in OAT cause the Finnish heritage disease gyrate atrophy (see “Results”)." (PMID 35347128, 2022). "Inherited mutations on the OAT gene lead to gyrate atrophy of the choroid and retina (GA), a rare recessive disease characterized by the degeneration of the choroid and the retinal epithelium." (PMID 34395527, 2021). "Gyrate atrophy is a rare metabolic autosomal recessive disorder caused by ornithine aminotransferase enzyme deficiency that leads to characteristic progressive, degenerative chorioretinal findings." (PMID 32159596, 2020). "Gyrate atrophy (GA) of the fundus is a rare, progressive metabolic disorder secondary to the deficiency of the pyridoxal phosphate-dependent enzyme, ornithine aminotransferase (OAT)." (PMID 30505995, 2018). "Gyrate atrophy (GA) of the choroid and retina is a rare autosomal recessive disorder that occurs due to deficiency of the mitochondrial enzyme ornithine aminotransferase (OAT)." (PMID 30429681, 2018). "Although the main metabolic roles of OAT are now quite well understood, they do not explain all the reported observations—for instance, the relationship between OAT mutation and the pathophysiology of gyrate atrophy remains poorly understood." (PMID 28272331, 2017). "Ornithine aminotransferase (OAT) deficiency or gyrate atrophy (GA; McKusick 258870) is an inherited deficiency of ornithine aminotransferase." (PMID 24422943, 2014). "In humans, OAT deficiency causes gyrate atrophy, a serious inherited disease." (PMID 28272331, 2017). "Given that inherited OAT deficiency is characterized by gyrate atrophy of the choroid and retina, long-term OAT inhibition as therapeutic strategy might bear the risk of inducing iatrogenic gyrate atrophy." (PMID 30199544, 2018). "Gyrate atrophy (OAT, OMIM #613349: autosomal recessive) is a rare IRD characterized by progressive vision loss due to mutations in the ornithine aminotransferase (OAT) gene." (PMID 38610844, 2024). "The deficit of human ornithine aminotransferase (hOAT) is responsible for gyrate atrophy (GA), a rare recessive inherited disorder." (PMID 34395527, 2021). "Deficit of human ornithine aminotransferase (hOAT), a mitochondrial tetrameric pyridoxal-5′-phosphate (PLP) enzyme, leads to gyrate atrophy of the choroid and retina (GA)." (PMID 36834788, 2023).
hepatocellular carcinoma (12 papers, 2008 to 2026). A malignant tumor that arises from hepatocytes. "OAT gene has been pinpointed as a potential biomarker and a target for therapy in human cancers such as gastric cancer, hepatocellular carcinoma, and non-small cell lung cancer." (PMID 40694220, 2025). "Ornithine aminotransferase (Oat; an enzyme that produces glutamate via ornithine) has been shown to be upregulated in hepatocellular carcinomas but has different activity in the intestine, where it produces citrulline and arginine instead of glutamate." (PMID 38730628, 2024). "In case of supraphysiologic OAT activity, potential risks of cancer should also be considered because OAT has been found to be overexpressed in hepatocellular carcinoma and in vivo inhibition of OAT has an antitumor effect in mice." (PMID 36647689, 2023). "Previously, it has been found by subtractive hybridisation that the transcript of OAT is up-regulated in hepatocellular carcinomas." (PMID 18544163, 2008). "Similarly, as we demonstrated for metastatic MDA-MB-231 cell line, OAT is overexpressed in hepatocellular carcinoma, and the inhibition of this enzyme has been suggested to be an effective therapy in mice." (PMID 33499132, 2021). "We previously found that the OAT gene was overexpressed in spontaneous hepatocellular carcinoma (HCC)-developing livers from sand rats." (PMID 36770800, 2023). "Ornithine aminotransferase (OAT) is overexpressed in hepatocellular carcinoma (HCC), and we previously showed that inactivation of OAT inhibits the growth of HCC." (PMID 36770800, 2023). "It has been shown that in hepatocellular carcinoma (HCC), the expression of OAT is up-regulated and the mechanism of this gene up-regulation is related to the activation of β-catenin signalling." (PMID 33536086, 2021). "We also highlight similar effects at the ornithine aminotransferase (Oat) and liver-specific glycogen synthase (Gys2) genes, indicating that these metabolic genes also are direct TCF7L2-regulated genes in hepatoma cells." (PMID 25414334, 2014). "Ornithine aminotransferase (OAT), a pyridoxal 5'-phosphate (PLP)-dependent enzyme, is a key contributor to glutamine supply in cancer cells, suggesting its therapeutic potential for hepatocellular carcinoma (HCC), the most common form of liver cancer." (PMID 42078119, 2026).
Hyperammonemia (4 papers, 2012 to 2023). An increased concentration of ammonia in the blood. "Therefore, deficiency of OAT activity in newborns can cause hyperammonemia because of deficiency in synthesis of ornithine, that is required by the urea cycle." (PMID 36647689, 2023). "Strikingly, hyperammonemia caused a massive elevation of glutamate concentrations associated with depletion of ornithine and 2-oxoglutarate, pointing at transamination processes via OAT as important pathophysiological basis of NH4+-induced toxicity." (PMID 30199544, 2018). "OAT deficiency at this age thus theoretically causes an increase in Pro and a deficiency of Orn and its products Arg and Cit (resulting in impairment of the urea cycle and attendant hyperammonemia), and so the Pro/Cit ratio increases." (PMID 28272331, 2017). "OAT deficiency should be added to the differential diagnosis of hyperammonemia in newborns, and the Pro/Cit ratio, which is easy to determine, could be valuable for GA screening and diagnosis in this neonatal period." (PMID 28272331, 2017). "Although further studies are needed to confirm this protective effect, OAT inhibition seems of interest as an approach to treating hyperammonemia." (PMID 28272331, 2017). "Increases in abundance of three other proteins contribute to a potential mechanism for liver damage induced by the consumption of excess dietary fat Ornithine aminotransferase (OAT) is a potential target for the treatment of hyperammonemias." (PMID 33907358, 2012). "Moreover, retinal degeneration has been anecdotally reported in patients with hyperornithinemia–hyperammonemia–homocitrullinuria syndrome (HHH syndrome) that have increased ornithine concentrations in blood despite normal OAT activity." (PMID 36647689, 2023). "Thus, OAT inhibition is a promising and effective therapeutic approach for preventing neurotoxicity and mortality in acute hyperammonemia." (PMID 30199544, 2018). "Surprisingly, in contrast to what is observed in mice neonates, loss of OAT activity in human newborns (although it leads to seizures due to hyperammonemia, and slower growth) is non-lethal." (PMID 28272331, 2017). "Intriguingly, specific and irreversible inhibition of ornithine aminotransferase (OAT) by 5-fluoromethylornithine rescues zebrafish from lethal concentrations of ammonium acetate and corrects hyperammonemia-induced biochemical alterations." (PMID 30199544, 2018). "To assess whether OAT inhibition might be a more effective therapeutic strategy against hyperammonemia-induced toxicity and mortality, we tested 5-FMO, a specific and irreversible OAT inhibitor." (PMID 30199544, 2018).
idiopathic pulmonary fibrosis (4 papers, 2010 to 2025). Idiopathic pulmonary fibrosis (IPF) is a nonneoplastic pulmonary disease that is characterized by the formation of scar tissue within the lungs in the absence of any known cause. "Upregulation of OAT in BLM-induced lung fibrosis mice further produced high level of proline by metabolizing excessive ornithine." (PMID 33995084, 2021). "In idiopathic pulmonary fibrosis models, overexpression of OAT could promote the production of mtROS by activating proline dehydrogenase, in turn activating TGF-β signals." (PMID 40694220, 2025). "The OAT inhibitor L-canaline attenuated lung fibrosis in a BLM-treated mouse model." (PMID 38413821, 2024). "This is based on the following: 1) CAT2 is upregulated in bleomycin-induced pulmonary fibrosis and 2) arginase metabolizes arginine to ornithine, which can be further metabolized by ornithine aminotransferase to proline, an amino acid that is often the rate-limiting substrate for collagen synthesis." (PMID 20576117, 2010). "We investigated whether inhibition of OAT could prevent experimentally induced lung fibrosis." (PMID 38413821, 2024).
breast carcinoma (3 papers, 2013 to 2025). "Knocking down ARG2 in breast cancer cells significantly inhibits cell proliferation and causes G2/M arrest, without compensation through the OAT pathway." (PMID 39973065, 2025). "Breast cancer cells rely on ARG2 for ornithine synthesis, while normal cells use ornithine aminotransferase (OAT)." (PMID 39973065, 2025).
Hyperornithinemia (3 papers, 2021 to 2024). Increased concentration of ornithine in the blood. "Blood tests confirmed hyperornithinemia and genetic analysis revealed two heterozygous mutations on ornithine aminotransferase (OAT) gene." (PMID 33602140, 2021). "This rare genetic disease is caused by defects in the ornithine-degrading mitochondrial enzyme, ornithine delta-aminotransferase (OAT, OMIM 613349), which leads to hyperornithinemia in the plasma." (PMID 34831381, 2021).
non-small cell lung carcinoma (3 papers, 2012 to 2025). A group of at least three distinct histological types of lung cancer, including non-small cell squamous cell carcinoma, adenocarcinoma, and large cell carcinoma. "The aim of this study is to detect the mRNA and protein expression of OAT in non-small cell lung cancer (NSCLC), as well as to analyze the bioinformatic features and binary interactions." (PMID 22989455, 2012).
colitis (2 papers, 2012 to 2019). Inflammation of the colon. "No significant protective effect of these two amino acids was observed, indicating that Arg supplementation inhibits colitis independently of the arginase/GATM/OAT metabolic pathway." (PMID 30972302, 2019). "There was also a decrease in OAT expression, and a modest decrease in L-Pro levels with L-Arg treatment in DSS colitis, also suggesting that L-Arg was not exerting its effects via L-Orn metabolism." (PMID 22428068, 2012).
fibrosis (2 papers, 2024 to 2025). the formation of excess fibrous connective tissue in an organ or tissue in a reparative or reactive process. "The OAT inhibitor L-canaline significantly attenuated bleomycin-induced lung injury and fibrosis." (PMID 38413821, 2024).
lung carcinoma (2 papers, 2020 to 2021). "Furthermore, OAT knockout nude mice exhibited significantly suppressed growth and metastasis of lung cancer xenografts." (PMID 33499132, 2021). "OAT stimulated the proliferation, migration, and invasion and blocked the apoptosis, while the lack of OAT reduced the growth and metastasis of lung cancer xenograft." (PMID 32590878, 2020).
pancreatic cancer (2 papers, 2019 to 2025). "In CAPG-overexpressing pancreatic cancer cells, phosphorylation status of other actin-modulating proteins (cofilin, ezrin/radixin) was not significantly altered, suggesting possible involvement of other cellular proteins, such as ornithine aminotransferase and enolase." (PMID 31360146, 2019).
retinal degeneration (2 papers, 2023). Degeneration of the retina. "The researchers showed that the restoration of at least 10% of OAT activity in the liver was sufficient to achieve significant improvement in ornithine concentration and prevent retinal degeneration." (PMID 36846970, 2023). "The consideration for the timing of vector administration should be carefully balanced between the desire to treat patients in late childhood or adulthood to achieve persistently high levels of OAT expression and earlier treatment to pre‐empt the onset of retinal degeneration." (PMID 36846970, 2023).
Azoospermia (1 paper, 2013). Absence of any measurable level of sperm,whereby spermatozoa cannot be observed even after centrifugation of the semen pellet. "Similarly, a stratified analysis on the basis of infertility phenotype did not reveal any significant association between this SNP and azoospermia or OAT." (PMID 23874907, 2013).
Blindness (1 paper, 2023). Blindness is the condition of lacking visual perception defined as a profound reduction in visual perception. "GACR is a severe and progressive form of blindness caused by deficiency of OAT that results in a systemic increase in ornithine concentrations." (PMID 36647689, 2023).
colon cancer (1 paper, 2001). "We identified 7 known genes (focal adhesion kinase, deleted in colon cancer, guanine binding inhibitory protein α, glutamine synthetase, ornithine aminotransferase, M130, and pepsinogen C) and 2 previously unknown genes as being overexpressed in HCC, and 1 gene (decorin) as suppressed in HCC." (PMID 11461082, 2001).
endotoxemia (1 paper, 2017). "Because of its place at the crossroads of Arg and Gln synthesis, it has been suggested that OAT could play a role in the adaptive response in early endotoxemia." (PMID 28272331, 2017).
Eosinophilia (1 paper, 2007). "Eosinophilia in curcumin-treated mice was markedly reduced, co-stimulatory molecule expression (CD80, CD86, and OX40L) on antigen-presenting cells was decreased, and expression of MMP-9, OAT, and TSLP genes was also attenuated." (PMID 17254346, 2007).
hepatic diseases (1 paper, 2012). "Although the expression of OATs is affected (mainly down-regulated) in certain renal and hepatic diseases, to our knowledge, no studies have been performed indicating changes in OAT functionality at the BBB." (PMID 22316420, 2012).
Huntington disease (1 paper, 2025). Huntington disease (HD) is a rare neurodegenerative disorder of the central nervous system characterized by unwanted choreatic movements, behavioral and psychiatric disturbances and dementia. "However, changes in ornithine aminotransferase levels have only been observed in glutamatergic neurons and associated with Huntington’s disease, suggesting a role for OAT in the synthesis of the neurotransmitter glutamate." (PMID 40539219, 2025).
keloid (1 paper, 2023). An irregularly shaped, elevated mark on the skin caused by deposits of excessive amounts of collagen during wound healing. "We observed that human fibrotic tissues (hypertrophic scar and keloid) have higher expression of Arg1, OAT and PYCR1 than normal skin." (PMID 37752116, 2023).
melanoma (1 paper, 2012). A malignant, usually aggressive tumor composed of atypical, neoplastic melanocytes. "However, OAT, which can generate P5C from ornithine, is expressed at similar levels in melanoma and melanocytes." (PMID 23024808, 2012).
nematodes infection (1 paper, 2021). "Metabolic pathways and biosynthesis of antibiotics may also be associated with T. gallinae infections probably due to the function of genes like UGP2 and OAT that were reported to play a role in nematodes infection and inhibiting Toxoplasma gondii." (PMID 34595226, 2021).
ovarian carcinoma (1 paper, 2025). A malignant neoplasm originating from the surface ovarian epithelium. "qRT-PCR assay was performed to examine the expression of OAT in human ovarian cancer cell samples and normal ovarian epithelial cells." (PMID 40694220, 2025). "Following the qRT-PCR assay, overexpressed OAT mRNA was determined in A2780 and SKOV3 human ovarian cancer cell lines compared to the normal IOSE-80 ovary cells (p < 0.05)." (PMID 40694220, 2025).
parasitic infections (1 paper, 2014). "In our experiment, the OAT but also the N(G),N(G)-dimethylarginine dimethylaminohydrolase 1 (DDAH1, a NOS inducer) proteins were less abundant during the infection suggesting that the NOS regulation is altered by the infection as it has been observed in several parasitic infections." (PMID 24967735, 2014).
pleural mesothelioma (1 paper, 2021). A neoplasm that arises from the mesothelial cells of the pleura. "We collected the methylation profile of pleural mesothelioma, and found 8 novel interactors to be hypomethylated in pleural mesothelioma versus non-tumor pleural tissue, namely, ACVR1B, IL6, MGMT, NRG1, OAT, PHLDA2, PLAUR and TNC." (PMID 33916178, 2021).